GLRA3 (glycine receptor alpha 3)
Description:
Glycine receptors are ligand-gated chloride channels. Channel opening is triggered by extracellular glycine. Channel characteristics depend on the subunit composition; heteropentameric channels display faster channel closure (By similarity). Plays an important role in the down-regulation of neuronal excitability (By similarity). Contributes to the generation of inhibitory postsynaptic currents (By similarity). Contributes to increased pain perception in response to increased prostaglandin E2 levels (By similarity). Plays a role in cellular responses to ethanol (By similarity).
Tractability: Small molecule: a structure with a bound ligand is known; a high-quality ligand is known; it belongs to a druggable protein family. Antibody: UniProt places it where antibodies can reach, with high confidence; its Gene Ontology location is reachable by antibodies, with high confidence; UniProt predicts a signal peptide or a membrane-spanning region. PROTAC: a small molecule that binds it is known.
Target class: Ion channel; Ligand-gated ion channel; Glycine receptor
Gene: Protein-coding gene on chromosome 4 (174,636,920 to 174,829,247, reverse strand). Ensembl gene ENSG00000145451.
Subcellular location: Postsynaptic cell membrane; Perikaryon; Cell projection, dendrite; Synapse; Cell membrane
Subcellular location (Human Protein Atlas): Plasma membrane; Vesicles
Pathways (Reactome):
Neuronal System: Neurotransmitter receptors and postsynaptic signal transmission
Gene Ontology:
Molecular function: extracellularly glycine-gated chloride channel activity; glycine-gated chloride ion channel activity; protein binding; excitatory extracellular ligand-gated monoatomic ion channel activity; extracellular ligand-gated monoatomic ion channel activity; glycine binding; monoatomic ion channel activity; transmembrane signaling receptor activity; transmitter-gated monoatomic ion channel activity
Biological process: chloride transmembrane transport; protein homooligomerization; chloride transport; excitatory postsynaptic potential; monoatomic ion transmembrane transport; monoatomic ion transport; presynaptic modulation of chemical synaptic transmission
Cellular component: glycine-gated chloride channel complex; plasma membrane; glycinergic synapse; perikaryon; postsynaptic membrane; synapse; dendrite; membrane; presynaptic membrane
Genetic constraint (gnomAD): Loss-of-function variants: 13 observed, 16.62 expected, observed/expected ratio (o/e) 0.78, 90% interval 0.51 to 1.24. The upper end of that interval is the gene's LOEUF score, 1.24, which puts it in group 5 of 6, group 1 being the genes least tolerant of losing a copy. Missense variants: 164 observed, 196.93 expected, observed/expected ratio (o/e) 0.83, 90% interval 0.73 to 0.95. Synonymous variants: 83 observed, 67.11 expected, observed/expected ratio (o/e) 1.24, 90% interval 1.03 to 1.48.
Homologues: Orthologues: chimpanzee GLRA3 (100% identical), macaque GLRA3 (100% identical), dog GLRA3 (99% identical), mouse Glra3 (99% identical), pig GLRA3 (99% identical), rat Glra3 (98% identical), guinea pig GLRA3 (98% identical), rabbit GLRA3 (98% identical), tropical clawed frog glra3 (83% identical), zebrafish glra3 (82% identical). Paralogues in human: GLRA1 (80% identical), GLRA2 (76% identical), GLRB (48% identical), GABRB3 (37% identical), GABRB2 (36% identical), GABRA4 (35% identical), GABRA1 (35% identical), GABRB1 (35% identical), GABRR2 (35% identical), GABRA2 (34% identical), GABRA6 (34% identical), GABRR1 (34% identical), and 33 more.
Diseases named in the same sentence as GLRA3 in open-access papers:
GLRA3 is named in the same sentence as 30 diseases in open-access papers, as found by Europe PMC text mining. Sharing a sentence is not in itself a finding about the gene and the disease. The quoted sentences say what the papers report.
endometriosis (2 papers, 2023 to 2024). The growth of functional endometrial tissue in anatomic sites outside the uterine body. "This study investigates the role and mechanism of Glycine receptor alpha 3 (Glrα3) in the central sensitization of pain in endometriosis, aiming to identify new therapeutic targets." (PMID 39125713, 2024). "Moreover, the expression of Glra3 and immunohistochemical detection of GLRA3 are increased in the insular cortex of female mice in an endometriosis model." (PMID 37264306, 2023).
type 1 diabetes (2 papers, 2018 to 2022). "In this study, the association between the common rs10011025 variant in the GLRA3 locus, and albuminuria, was confirmed in 1259 independent Finnish individuals with type 1 diabetes (p = 0.0013), and meta-analysis of all Finnish individuals yielded a genome-wide significant association." (PMID 30120300, 2018). "We have previously identified genetic variants in the GLRA3 gene to be genome-wide significantly associated with AER in a Finnish GWAS discovery population (rs10011025 p = 1.5 × 10−9), but we were not able to replicate the signal in 598 additional Finnish individuals with type 1 diabetes." (PMID 30120300, 2018). "On the contrary, a replication attempt in 3152 non-Finnish European individuals with type 1 diabetes reached a nominally-significant p-value of 0.03 for a directly genotyped SNP, rs1564939 in the GLRA3 gene, but with the opposite allele associated with albuminuria than in the Finnish subjects." (PMID 30120300, 2018).
epilepsy (1 paper, 2024). A brain disorder characterized by episodes of abnormally increased neuronal discharge resulting in transient episodes of sensory or motor neurological dysfunction, or psychic dysfunction. "Interestingly, glycine receptor alpha 3 (Glra3) and dopamine receptor D1 (Drd1) were genes involved in more than two annotations related to epilepsy." (PMID 38338984, 2024).
injury (1 paper, 2024). Damage inflicted on the body as the direct or indirect result of an external force, with or without disruption of structural continuity. "Meanwhile, deletion/mutation of Glra3 does not affect the withdrawal response to mechanical and thermal stimulation following nerve injury." (PMID 38553047, 2024).
itch (1 paper, 2024). "In conclusion, these results show that spinal Glra3(+) neurons contribute to acute communication of compound 48/80- and chloroquine-induced itch in hairy skin." (PMID 38553047, 2024). "Besides input from itch-related primary afferents, the monosynaptic tracing experiments and dorsal root stimulations revealed that the Glra3-Cre populations receive input from Aα∕β fibers as partial overlap with NF200(+)." (PMID 38553047, 2024). "Behavioral and expressional analyses revealed that spinal Glra3-Cre populations have a pro-pruritic role in compound 48/80- and chloroquine-evoked itch and no role in the mechanical or thermal responses that have been tested in this study." (PMID 38553047, 2024). "In conclusion, the Glra3-Cre populations have a pro-pruritic role in compound 48/80- and chloroquine-evoked itch, while not involved in acute noxious mechanical or thermal transmission." (PMID 38553047, 2024). "Altogether, these findings verify that Glra3(+) neurons are involved in the communication of compound 48/80- and chloroquine-induced itch and that these neurons are not involved in acute mechanical or thermal transmission." (PMID 38553047, 2024).
Obesity (1 paper, 2025). Accumulation of substantial excess body fat. "In another study, a GWAS conducted on 1996 adult CCS (median age at diagnosis, 7.2 years; median age at follow-up, 32.4 years) identified potential obesity-associated loci on chromosomes 13 (FAM155A), 2 (SOX11), 4 (GLRA3), and 5 (CDH18, BASP1), particularly among CRT-exposed survivors." (PMID 41228239, 2025).
rectal cancer (1 paper, 2023). A primary or metastatic malignant neoplasm that affects the rectum. "Interestingly, this miRNA regulates unique genes from all three anatomical locations, including CHGB in the right colon, CACNA1B and GLRA3 in the left colon, and TFAP2B in rectal cancer." (PMID 37987361, 2023).
GLRA3 also shares sentences with these, for which no sentence is quoted: Alzheimer disease (3 papers); cancer (3); schizophrenia (3); tumor (3); cognition disorders (2); depression (2); asthma (1); autoimmune thyroid disease (1); bipolar disorder (1); channelopathy (1); dry mouth (1); epileptic encephalopathies (1); hepatitis C (1); infection (1); irritable bowel syndrome (1); myopia (1); neurological disorders (1); nicotine addiction (1); peripheral neuropathy (1); rheumatoid arthritis (1); sleep disorder (1); spinocerebellar ataxia (1); Stroke (1).